INS (insulin)
Diseases named in the same sentence as INS in open-access papers (continued):
Sharing a sentence is not in itself a finding about the gene and the disease.
colorectal cancer (continued). "Diverse in vitro and in vivo studies have shown that insulin and Insulin-like Growth Factor (IGF-1) have mitogenic effects on colorectal cancer cells, stimulating cell proliferation and inhibiting apoptosis." (PMID 33672318, 2021). "Mechanically, MTMR7 inhibits insulin-mediated AKT-ERK1/2 signaling, which in turn decreases colorectal cancer cell proliferation." (PMID 33282950, 2020). "Insulin and the IGF system play key roles in colorectal cancer development, progression, and prognosis." (PMID 32466596, 2020). "Akt activation by insulin produced markedly lower levels of LC3-II conversion in the TCO-treated cells than in the controls, suggesting that TCO induced autophagy in colorectal cancer cells by inhibition of the Akt/mTOR pathway." (PMID 28881770, 2017). "The insulin/insulin-like growth factor (IGF) system is a major determinant in the pathogenesis and progression of colorectal cancer (CRC)." (PMID 26528439, 2015). "We then applied these methods to data from a previously published case-cohort investigation of the insulin/IGF-axis and colorectal cancer." (PMID 23834739, 2013). "Both insulin and IGF-1 are potent mitogens that promote colorectal cancer cell growth and survival in vitro, and elevated blood levels of IGF-1 and insulin are associated with increased risk of developing colorectal cancer." (PMID 21081932, 2011). "Hyperinsulinemia is a condition of increased levels of circulating insulin in the blood, ultimately increasing the availability of insulin-like growth factor (IGF)-I to the IGF-I receptor, which is crucial in the development of colorectal cancer." (PMID 40457130, 2025). "For example, among insulin nonusers, the adjusted OR of patients with colorectal cancer to their matched controls was 1.92 (95% CI = 1.16–3.18)." (PMID 35600378, 2022). "On the other hand, the role of Insulin/IGF signaling in the acquisition of the Warburg metabolic phenotypes in colorectal cancer cells is still not fully described." (PMID 34208601, 2021). "Moreover, our study suggests that in early stage colorectal cancer stringent glucose control may be important for tumor progression, while in advanced stages of colon cancer inhibition of the endocrine actions of the IGFs and insulin are more important to restrain growth of colon cancer cells." (PMID 34290976, 2021). "Our data suggest that insulin enhances the effect of chemotherapeutic agents in colorectal cancer while showing no toxicity." (PMID 31719636, 2019). "Among 4902 non-diabetic women with baseline fasting serum insulin and glucose values, 81 incident cases of colorectal cancer were identified over 12 years of follow-up." (PMID 22127286, 2012). "In conclusion, in this cohort study of postmenopausal women, elevated fasting serum glucose, but not insulin or HOMA-IR, was associated with roughly a two-fold increased risk of colorectal cancer." (PMID 22127286, 2012). "During a median follow-up period of 11.9 years (0.05–15.4), a total of 81 colorectal cancer cases were ascertained in the cohort of 4902 non-diabetic women with fasting serum insulin and glucose values at baseline." (PMID 22127286, 2012). "Our results suggest that IGFs and insulin are especially important for growth of advanced colorectal cancer cells which have metastasized, but they seem not to play an important role in the early growth of colon cancer cells localized and confined to the bowel." (PMID 34290976, 2021). "This counterintuitive result was well exemplified by the cases of ZEB2 and RAS in the EMT regulatory network, IRS in the signaling network of EGF-EGFR and insulin-IR, MEK and GRB2 in the signaling network of T-LGL leukemia survival, p21 and PDK1 in F2013, and MEK in C2016 colorectal cancer networks." (PMID 31582789, 2019). "Besides, in vivo researches about the administration of 2DG with and without insulin are needed to investigate not only the anticancer efficiency on colorectal cancer but also the effect on blood glucose level." (PMID 26939025, 2016).
colorectal cancer (continued). "The mean (SD) follow-up time for the outcome of colorectal cancer was 2074.7 (435.3) days for the GLP-1RA/no insulin group and 1981.8 (471.1) days for the insulin/no GLP-1RA group." (PMID 38967919, 2024). "The Table shows the characteristics of the GLP-1RA/no insulin and insulin/no GLP-1RA groups before and after propensity-score matching for covariates related to colorectal cancer." (PMID 38967919, 2024).
MODY (204 papers, 2009 to 2026). "Hypoinsulinemia in insulin variants is found in maturity-onset diabetes of the young type 10 (MODY 10) and neonatal diabetes." (PMID 36028536, 2022). "Using insulin mutagenesis of neonatal diabetes variant-C43G and maturity-onset diabetes of the young 10 (MODY10) variant-R46Q, UDP-glucose:glycoprotein glucosyltransferase 1 (UGGT1) protects cereblon-dependent proinsulin ubiquitination in the ER." (PMID 36028536, 2022). "Patients with maturity-onset diabetes of the young (MODY) were shown to have noncoding mutations within the BLK locus which resulted in disruption in insulin synthesis when glucose levels were high." (PMID 29922517, 2018). "Including replication in additional MODY patients, we identified eight families with 17 affected individuals carrying INS variants." (PMID 41772234, 2026). "In contrast, MODY subtypes, including MODY 3, typically preserve some degree of endogenous insulin production, rendering the risk of DKA exceedingly low under normal physiological circumstances." (PMID 41367451, 2025). "We present a case of MODY arising from a novel disease-causing INS variant, in an adolescent with atypical features." (PMID 39717432, 2025). "Functionally defective mutation of HNF4α causes the maturity-onset diabetes of the young (MODY), which is characterized by pancreatic β-cell dysfunction and impaired insulin secretion." (PMID 40940746, 2025). "Caused by heterozygous mutations in various genes affecting insulin secretion, MODY can exhibit a wide range of clinical presentations." (PMID 40109403, 2025). "GCK-MODY is the most common type of MODY, and patients with INS variant account for a relatively large proportion of MODY cases in our cohort." (PMID 40303944, 2025). "INS variants remain a rare cause of MODY and affected individuals present with heterogenous clinical phenotypes, making an accurate diagnosis challenging." (PMID 39717432, 2025). "While T2DM is a multifactorial disease caused by mutations in various genes, MODY is primarily caused by mutations in genes essential for beta-cell function, leading to defects in insulin secretion." (PMID 40149950, 2025). "Taken together, this study shows that the MODY-associated Kcnk16 L114P mutation disrupts glucose homeostasis in adult mice resembling a MODY phenotype and causes neonatal lethality by inhibiting islet insulin secretion during development." (PMID 38700926, 2024). "Heterozygous missense mutations in the insulin gene are rare causes of MODY, and optimal treatment strategies remain uncertain." (PMID 39027635, 2024). "Pancreatic exocrine deficit has been reported in 20–75% of patients, and MODY is caused by beta-cell dysfunction and insulin resistance." (PMID 39337310, 2024). "Most mutations that are the main cause of MODY have low penetrance, while the effectiveness of therapies such as sulfonylurea derivatives and insulin has resulted in the majority of patients being cured." (PMID 39902162, 2024). "HNF1B-associated MODY accounts for approximately 6% of all MODY cases, characterized by declining insulin secretion leading to progressive hyperglycemia." (PMID 39337310, 2024). "Heterozygous pathogenic variants in the insulin gene are rare causes of MODY, and optimal treatment strategies remain uncertain." (PMID 39027635, 2024). "NUDT12 is associated with MODY, supporting its potential role in influencing diabetic peripheral neuropathy through affecting insulin and glucose homeostasis." (PMID 38464965, 2024). "To date, more than 20 genetic variants of monogenic MODY phenotypes have been identified, and a treatment strategy with insulin or its combination with glucose-lowering drugs from the sulfonylurea group has been defined for most forms." (PMID 39902162, 2024). "MODY is linked to the defects in pancreatic islet cell development and insulin secretion in young individuals." (PMID 35956399, 2022).
MODY (continued). "Mutations in KCNJ11 or ABCC8 that increase the opening probability of the channel hyperpolarise the beta cell membrane and inhibit insulin secretion, causing either neonatal diabetes or MODY." (PMID 35618782, 2022). "ProinsulinR46Q and proinsulinC43G genetic mutations associated with MODY/neonatal diabetes all cause impairment in arginine-inducing insulin secretion but cause distinct defects in the interaction between UGGT1 and proinsulin." (PMID 36028536, 2022). "LOF mutations in HNF1A, HNF1B and HNF4A, all leading to defective insulin secretion and reduced β-cells mass, cause some forms of MODY possibly associated with kidney and/or liver abnormalities." (PMID 35052457, 2022). "For example, the level of insulin sensitivity in MODY caused by variants in HNF1A (HNF1A-MODY) depends on the comparator group and their genetic background, perhaps irrespective of HNF1A altogether." (PMID 34951657, 2022). "MODY is primarily caused by a defect in pancreatic β-cells’ glucose-stimulated insulin production, highlighting the critical functions of HNF1A and HNF4A in -cells." (PMID 36037214, 2022). "Maturity-onset diabetes of the young (MODY) is a heterogeneous group of disorders due to mutations in single genes involved in insulin metabolism." (PMID 33477627, 2021). "To date, 11 genes have been confirmed to cause MODY, all of which are involved in pancreatic β cell insulin secretion and all with autosomal dominant transmission." (PMID 34032641, 2021). "A study of birthweights from pregnancies affected by MODY due to a heterozygous mutation in the glucokinase gene (GCK) provided important insights into how the fetal genotype determines insulin-mediated growth in utero." (PMID 33569631, 2021). "Diverse genetic defects in GCK lead to different kinds of insulin secretion phenotypes, resulting in a range of disease severity, from neonatal diabetes and MODY, to increased T2D risk and congenital hyperinsulinism." (PMID 33828531, 2021). "Some INS coding mutations can also cause MODY and genetic variants in the INS/IGF2 locus have been associated with T2D increased risk." (PMID 33828531, 2021). "Maturity-onset diabetes of the young (MODY) is an dominant, autosomal genetic disease characterized by islet function defects, insufficient insulin secretion and islet-associated antibody negativity." (PMID 31322178, 2019). "Most other forms of MODY, neonatal diabetes and mitochondrial diabetes are characterised by insulin deficiency and therefore, in most cases, individuals progress to insulin therapy." (PMID 30377832, 2018). "In summary, the present study provides some insight into the structural and functional aspects of the Arg→Gln swap at the B22 position of insulin, a naturally occurring mutation (R46Q) that causes MODY." (PMID 25423173, 2014). "It is known that rare mutations in GCK occurring in MODY result from a reduced glucose-stimulated insulin secretion." (PMID 24728127, 2014). "The insulin gene mutation c.137G>A (R46Q), in which arginine at position B22 is replaced by glutamine, causes MODY, and has been identified to date in one Czech family and one Norwegian family." (PMID 25423173, 2014). "In MODY patients, this mutation is heterozygous, and both mutant and wild-type (WT) human insulin are produced simultaneously." (PMID 25423173, 2014). "Rare heterozygous inactivating mutations in GCK cause MODY, mainly due to a reduced glucose-stimulated insulin secretion." (PMID 24728127, 2014). "In contrast, MODY3 caused by HNF1A mutations, the most common type of MODY that accounts for ∼63% of all MODY cases, tends to have obvious glycosuria because of impaired glucose-stimulated insulin secretion, as well as decreased renal threshold for glucose." (PMID 25136813, 2014). "MODY patients have a heterozygous mutation, and both the mutant and WT insulin are produced simultaneously." (PMID 25423173, 2014).
MODY (continued). "Here, we have characterized a naturally occurring insulin analogue bearing the ArgB22→Gln mutation implicated in MODY." (PMID 25423173, 2014). "HNF1A-MODY is associated with a severe and progressive clinical course with up to 50% of patients requiring insulin." (PMID 22808921, 2012). "HNF1A MODY patients showed much a better response to gliclazide than the patients with T2DM and this difference was associated with a great insulin secretion improvement in MODY patients." (PMID 22996131, 2012). "This protein also controls the insulin secretory pathway and is linked to rare monogenic disorder, i.e. maturity-onset diabetes of the young (MODY)." (PMID 21829439, 2011). "Mutations in INS can be a rare cause of MODY and we conclude that screening for mutations in INS should be recommended in MODYX patients." (PMID 20226046, 2010). "Heterozygous NMD-escape LOF variants in INS are a novel cause of MODY." (PMID 41772234, 2026). "Furthermore, the KCNK16 Leu114Pro mutation related to MODY has been found to disrupt glucose regulation in adult mice, leading to a MODY-like phenotype and neonatal mortality by inhibiting insulin secretion in the islets during development." (PMID 40650956, 2025). "Many cases of MIDY and MODY require insulin therapy, however, MODY 1 and MODY 3, caused by mutations in the transcription factors hepatocyte nuclear factor 4α (HNF4A) and 1α (HNF1A), respectively, can often improve insulin secretion with sulfonylurea treatment." (PMID 40666490, 2025). "MODY represents the most common form of monogenic diabetes and is due to impaired development and function of pancreatic β cells, resulting in deficient secretion of insulin." (PMID 41356216, 2025). "Moreover, other studies have reported a contribute of other genetic factors in development of islet autoantibodies, including MODY genes, such as INS, that is considered the second strongest risk locus after HLA for T1D." (PMID 40540212, 2025). "Therefore, the seven documented DKA admissions over a nine-year period in this patient are notable and were likely precipitated by poor adherence to insulin therapy, as well as intrinsic insulin deficiency in pancreatic beta cells, an atypical finding of MODY." (PMID 41367451, 2025). "Moreover, another variant in the same PDX1 amino acid position (p.P33T) was described as associated with MODY and shown to lead to reduced binding to the insulin promoter and decreased transcriptional activity in vitro." (PMID 39364395, 2024). "However, INS-MODY variants were previously reported to be exceedingly rare in MODY patients worldwide." (PMID 39191897, 2024). "In various populations, mutations in the HNF1A gene are a common cause of the maturity-onset diabetes of the young (MODY), which is characterized by early age of onset and a marked defect in insulin secretion." (PMID 21208426, 2011). "Maturity-onset diabetes of the young (MODY) is a collection of uncommon monogenic insulin-secretion pathologies." (PMID 19216786, 2009). "Abnormalities in HNF4a are commonly associated with a high incidence of maturity-onset diabetes of the young (MODY), with MODY1 patients exhibiting defects in insulin secretion stimulated by glucose and arginine, indicating a progressive loss of pancreatic β-cell function." (PMID 40469443, 2025). "Even in HNF1B-MODY, where insulin is often the default, incretin therapy has shown promise: semaglutide has enabled insulin withdrawal, improved time-in-range, and modest weight loss, while tirzepatide has increased fasting C-peptide and dramatically reduced insulin needs." (PMID 41262822, 2025). "However, as these were short-term experiments, prolonged inhibition of β cell insulin secretion in individuals with MODY carrying the TALK-1 Leu114Pro mutation may result in increased insulin content." (PMID 34032641, 2021).